Y_RNA (Y RNA )
Gene: Miscellaneous RNA gene on chromosome 1 (99,791,662 to 99,791,753, forward strand). Ensembl gene ENSG00000202254.
Homologues: Orthologues: chimpanzee Y_RNA (100% identical), macaque Y_RNA (97% identical), guinea pig Y_RNA (91% identical). Paralogues in human: RNY3 (92% identical), Y_RNA (91% identical), Y_RNA (90% identical), RNY3P1 (89% identical), Y_RNA (89% identical), Y_RNA (88% identical), RNY3P16 (87% identical), Y_RNA (87% identical), RNY3P9 (86% identical), Y_RNA (86% identical), RNY3P11 (85% identical), RNY3P13 (85% identical), and 93 more.